SPARC (secreted protein acidic and cysteine rich)
Diseases named in the same sentence as SPARC in open-access papers (continued):
Sharing a sentence is not in itself a finding about the gene and the disease.
melanoma (continued). "Indeed, secreted SPARC by melanoma cells promotes vascular permeability and tumor cells expressing MGP present an increased adhesion ability to the endothelium." (PMID 30546831, 2018). "As in melanoma the EMT-like process is influenced by the action of SPARC, we evaluated whether SCD5 restored expression might be able to modulate the transcription factors playing a key role in this program." (PMID 29484133, 2018). "Although the molecular events responsible for their activity remain to be defined, the upregulation of PTN, RGS13, and SPARC in black color skin could explain the incidence of melanoma in light coat color horses." (PMID 28974924, 2018). "Inhibition of melanoma cell invasion by metformin is correlated with modulation of expression of proteins involved in epithelial-mesenchymal transition such as Slug, Snail, SPARC, fibronectin, and N-cadherin and with inhibition of MMP-2 and MMP-9 activation." (PMID 29245964, 2017). "To establish whether Rac1 might mediate SPARC effects on melanoma cell plasticity, we made use of a constitutively active Rac1 mutant (RacQL) and a dominant negative Rac1 mutant (RacDN) to modulate Rac1 activity." (PMID 26248315, 2015). "Indeed, previous studies have demonstrated that the inhibition of SPARC expression abrogated the tumorigenicity and metastatic dissemination of cancer cells in melanoma and glioma human xenografts tumors in nude mice." (PMID 26248315, 2015). "In this study we aimed to unravel a potential intracellular mechanism of action of SPARC that would help explain its diverse roles, focusing on human melanoma cells for which the role of SPARC as a pro-tumorigenic and pro-mesenchymal protein has been conclusively demonstrated." (PMID 26248315, 2015). "In melanoma cells, a regulation of Slug/SNAI2 by SPARC/osteonectin has been described, indicating that SPARC may promote EMT-associated tumor invasion by supporting AKT-dependent upregulation of SLUG." (PMID 23984088, 2013). "SPARC (secreted protein acidic and rich in cysteine) is found in the cell membrane and in medium of cultured melanoma cells, and downregulation of its expression in melanoma tumor xenografts by antisense RNA inhibits tumor growth." (PMID 23470450, 2013). "Thus, SLUG functionally contributes to SPARC-enhanced melanoma cell migration and E-cadherin repression." (PMID 22911700, 2012). "Furthermore, SLUG is a bona fide transcriptional repressor of E-cadherin as well as a regulator of P-cadherin in melanoma cells and its knockdown attenuated invasive behavior and blocked SPARC-enhanced cell migration." (PMID 22911700, 2012). "In particular, melanoma cells with suppressed SPARC expression resulted in enhanced polymorphonuclear leukocyte (PMN) recruitment, a first-line of defense in the immune surveillance against cancer, and in increased antitumor cytotoxic activity against tumor growth in vitro and in vivo." (PMID 22481923, 2012). "In melanoma, however, the expression of SPARC was positively correlated with angiogenesis." (PMID 22957090, 2012). "Additionally, the ablation of SPARC transcription using antisense RNA has successfully inhibited human melanoma and gastric cancer growth in nude mice." (PMID 22481923, 2012). "In addition, we provide here evidence that SPARC constitutes an important upstream regulator of P-cadherin in melanocytes and melanoma cells." (PMID 22911700, 2012). "Interestingly, SPARC also has a pro-tumorigenic function linking its expression with poor prognosis in certain human cancers such as melanoma, meningioma and prostate cancer." (PMID 20687958, 2010). "Indeed, expression of antisense oligonucleotides against SPARC in melanoma cells blocked tumor formation." (PMID 20525171, 2010).
melanoma (continued). "Thus, a CRAd driven by the SPARC promoter was therapeutically effective leading to the cure of more than 50% of mice harboring human melanomas composed of malignant cells alone." (PMID 19337591, 2009). "The role of SPARC in tumor progression is controversial although in certain types of human cancer such as glioblastoma and melanoma, SPARC overexpression in the malignant cells themselves has been associated with increased aggressiveness (and references therein)." (PMID 19337591, 2009). "However, recent evidence suggests that alterations in SPARC expression are common in various human malignancies, including melanoma, glioma, invasive meningioma, hepatocellular carcinoma, colon, breast, and prostate cancers." (PMID 14562024, 2003). "However, the impact of miR-29s on the regulation of SPARC expression in melanoma remains elusive." (PMID 40943659, 2025). "Hence, although further research is needed, we speculate that PRRX1 and the activation of β-catenin/TCF7L2 may regulate the maximal activation of the SPARC promoter in melanoma cells, and maybe that of other mesenchymal genes." (PMID 40943659, 2025). "We hypothesize that SPARC expression in melanomas may be driven by specific oncogenic signals and transcriptional activators of the invasiveness program; however, it may also depend, at least in part, on post-transcriptional regulation by specific microRNAs (miRs)." (PMID 40943659, 2025). "Thus, a SPARC-miR axis may orchestrate a fine regulation of SPARC protein levels along the transition between distinct phenotypic melanoma states." (PMID 40943659, 2025). "Thus, HDAC10 is the major HDAC that suppresses SPARC expression in melanoma cells." (PMID 38650694, 2024). "SPARC aids cell expansion and could be a possible target for melanoma treatment." (PMID 37577749, 2023). "SPARC could become a new target to stop the progression of melanoma." (PMID 37577749, 2023). "In addition, the successful control of melanomas by targeting SPARC expression further suggested that knockdown of SPARC in some malignancies, such as ESCC, may be one of the effective strategies for cancer therapy." (PMID 31897236, 2020). "With regard to cancer development, SPARC has been described as a tumorsuppressor in some tumor types (e.g., in ovarian or bladder cancer), while it was found overexpressed as a possible promoter of tumorigenesis in others (melanoma, breast cancer, and glioblastoma)." (PMID 31554208, 2019). "In order to identify the intracellular mechanisms by which SPARC might promote melanoma aggressiveness, we used established human melanoma cells where the knock down of SPARC expression was attained expressing either antisense RNA in human melanoma cells." (PMID 26248315, 2015). "We next examined whether silencing of SPARC in melanoma cells could affect SLUG protein levels." (PMID 22911700, 2012). "Indeed, increased SPARC expression has been described in multiple cancers, including colon, esophagus, pancreas, breast, lung, brain, bladder, renal, and melanoma." (PMID 19337591, 2009). "To confirm these results, we performed a Western blot of both melanoma cell lines after treatment with the JNK inhibitor, finding a significant reduction in SPARC protein." (PMID 40943659, 2025). "Other significantly reduced proteins include TRAIL, TGFR-2, ANXA1, SPARC, FURIN, GPNMB, and ERBB2, all of which play roles in melanoma progression, immune modulation, or resistance to targeted therapies." (PMID 40725203, 2025).
melanoma (continued). "Given the relevance of PRRX1 in the context of melanoma, we further examined the correlation between the PRRX1 and SPARC expression in two independent sets of our melanoma patients (cohorts I and II)." (PMID 40943659, 2025). "To further confirm that miR-29s act on the SPARC 3′ UTR, we co-transfected the luc-3′ UTR SPARCwt with specific anti-miR 29a, b, and c in the MeWo, SK-Mel 131, and WM 793 melanoma cell lines." (PMID 40943659, 2025). "Depletion of HDAC10 and the subsequent upregulation of SPARC activate AMPK signaling and induce autophagy, ultimately suppressing melanoma cell growth and attenuating resistance to BRAF inhibitors." (PMID 38650694, 2024). "To explore the potential relationship of HDACs and SPARC, we performed knockdowns of individual classical HDACs (HDAC1−11) in A375 melanoma cells using lentivirus-delivered shRNA." (PMID 38650694, 2024). "Our work reveals the role of HDAC10 in gene regulation through indirect histone modification and suggests a potential therapeutic strategy for melanoma or other cancers by targeting HDAC10 and SPARC." (PMID 38650694, 2024). "The melanoma (A375 and WM793) and lung cancer (H1299 and A549) cell lines were chosen for this study due to their differential SPARC protein expression levels." (PMID 38650694, 2024). "Next, Pearson correlation analysis combined with clinical evaluation using human melanoma data (TCGA‐SKCM) was performed to analyze the correlation between SEC23A, SPARC, and the 67 candidate gene targets of miR‐487a‐5p (Fig. 4Aa‐b)." (PMID 37356089, 2023). "Similarly, a previous study showed that the C-terminal extracellular Ca2+ module of SPARC, a domain implicated in binding to endothelial cells 69 and to vascular cell adhesion molecule 1 (VCAM1) 70, is needed to enhance endothelial transmigration of melanoma cells via VCAM1 signaling." (PMID 33995652, 2021). "SPARC promotes bone metastasis and EMT properties in highly-metastatic tumors, including triple-negative breast cancer, melanoma, and prostate cancers." (PMID 28718842, 2017). "Additionally, although ASCR control melanoma cells did not exhibit a highly organized actin cytoskeleton, SPARC-deficient AC3 cells showed a marked actin cytoskeleton rearrangement with increased formation of filopodial projections compared to ASCR control cells." (PMID 26248315, 2015). "A previous study found that the invasive ability of melanoma cells was positively correlated with the level of MMP-2 and that SPARC can induce invasive breast cells to produce MMP-2." (PMID 23516489, 2013). "In this work, we studied further the interplay between SPARC, E- and P-cadherin repression and EMT-like induction in melanoma cells." (PMID 22911700, 2012). "Our previous study also found that SPARC regulates SNAIL expression in melanocytes and melanoma cells." (PMID 22911700, 2012). "In conclusion, we report here the first demonstration of a regulation of the lineage-specific developmental factor SLUG by SPARC through an AKT-dependent pathway and the importance of this mechanism in EMT-induced cell invasion in melanoma." (PMID 22911700, 2012). "Because siRNA SPARC-induced migratory inhibition coincides with SLUG reduction, we next analyzed the effect of SLUG knockdown on melanoma cell migration and invasive behavior." (PMID 22911700, 2012). "We previously showed that SPARC induces E-cadherin repression and EMT-like processes in melanocytes and melanoma cells." (PMID 22911700, 2012).
melanoma (continued). "Collectively, these data indicate that SPARC-induced EMT-like transition in melanocytes and melanoma cells is accompanied by upregulation of SLUG, and suggest that SPARC functions by maintaining the augmented expression of SLUG in melanomas." (PMID 22911700, 2012). "The recent observation that SPARC stimulates PI3 kinase/AKT-dependent pathway in A375 melanoma cells prompted us to examine the role of this pathway in SPARC-driven SLUG expression and promotion of melanoma cell migration." (PMID 22911700, 2012). "Keeping in mind that phenotype switching in melanoma cells entails the exclusive expression of β-catenin cofactors LEF1 or TCF7L2, we interrogated whether SPARC can be integrated into this process, either in the presence or absence of PRRX1 expression." (PMID 40943659, 2025). "Similarly, in melanoma, HDAC10 inhibitors were shown to enhance tumor sensitivity to BRAF inhibitors by upregulating SPARC expression, a key factor in modulating the tumor microenvironment." (PMID 40657362, 2025). "This fusion was carried out to exploit the properties of the Secreted Protein Acidic and Rich in Cysteine (SPARC), which is an anti-adhesive and promigratory matricellular glycoprotein that is abundantly expressed in aggressive forms of melanoma, breast, brain, prostate, colon, and lung cancers." (PMID 40428088, 2025). "To this end, we first performed chromatin immunoprecipitation and found that TCF7L2 was significantly enriched in the SPARC promoter region (−175 to −25 nt relative to the TIS) in several melanoma cell lines tested, whereas LEF1 was not." (PMID 40943659, 2025). "The growth of melanoma is not regulated by exogenous SPARC or by stromal tissue, but solely by the amount of SPARC that is yield by the malignant cells themselves." (PMID 37577749, 2023). "Through leveraging gene signatures in predicting the durability of drug response, this study also identified the expression levels of the genes MMP2, SPARC, and HMOX1 as having a good predictive value in predicting the emergence of chemoresistance to BRAF/MEK inhibitor therapy in melanomas." (PMID 37176114, 2023). "Furthermore, SPARC can act cooperatively to enhance the inhibition of Pf4 on ERK phosphorylation and melanoma cell metastasis." (PMID 34421345, 2021). "Contrasting these findings, SPARC expression was down-regulated in malignant melanoma that failed to respond to the chemotherapeutic agent dacarbazine with the authors concluding that expression of SPARC promoted effective tumour immunity." (PMID 33187209, 2020). "Secreted protein acidic and rich in cysteine (SPARC) was deepened in the tumorigenicity and progression of melanoma, resulting as a nonstructural matricellular protein." (PMID 33050185, 2020). "We found that treatment of some melanoma cell lines (SK-Mel 28, HTB66 and Lox,) but not all (not Yusac2, Yugen 8 or WM793, data not shown) with MSA caused a decrease in SPARC both in cell lysates and in the medium." (PMID 23470450, 2013). "Finally, we have examined the expression profiles of SPARC and SLUG in a small panel of cultures of melanoma cells derived from RGP or VGP primary tumors or from lymph node melanoma metastases." (PMID 22911700, 2012). "F512Pr exhibited the highest luciferase activity (1.7 to 4.9 - fold induction over SV40 promoter) in melanoma cell lines that do express high SPARC mRNA levels although no strict relationship was observed between SPARC mRNA levels and promoter activity." (PMID 19337591, 2009). "Either CRAd, expressing or not TK were cytotoxic in vitro on a panel of melanoma cell lines expressing SPARC." (PMID 19337591, 2009). "Since the in silico analysis indicated the presence of LEF/TCF (T cell factor/Lymphoid Enhancer factor)-binding sites “A/T A/T CAAAG” within the SPARC proximal promoter, we explored whether endogenous LEF1 or TCF7L2 TFs could bind to this promoter region in melanoma cells." (PMID 40943659, 2025).
melanoma (continued). "Additionally, SPARC, an identified EMT marker that promotes EMT in tumorigenesis by regulating TGFβ signaling, was predominantly expressed within the invaded cell islands with stronger expression in both the melanoma and HNSCC RF-FTMs." (PMID 36232952, 2022). "As SPARC is involved in the transition from epithelial to mesenchymal phenotypes, we have hypothesized the possible contribution of SCD5 in reversing the EMT-like process described in melanoma." (PMID 29484133, 2018). "The relevance in human tumor progression of a cell-autonomous pro-metastatic function of SPARC is supported by its expression by the cancerous components of metastatic primary tumor samples of glioblastoma, melanoma and prostate cancer, but not in samples from non-metastatic primary tumors." (PMID 25331979, 2014). "This is consistent with SPARC activation of an MMP which could in turn cleave and inactivate an as yet unidentified death receptor ligand that is responsible for the caspase-8 activity observed after treatment of melanoma cells with MSA." (PMID 23470450, 2013). "In addition, in vitro analysis of moles removed during the follow-up of NTZ-treated MS patients showed a reduced expression of secreted acidic cysteine-rich protein (SPARC) and β3 integrin on melanocytic cells, proteins that are normally able to promote melanoma invasiveness." (PMID 39274345, 2024). "In transwell assays, melanoma-derived SPARC inhibited the migration of neutrophils but not lymphocytes or monocytes, suggesting that elevated SPARC production may allow melanoma cells to escape immune-mediated destruction by selectively inhibiting neutrophil influx." (PMID 33187209, 2020). "Also, in view of our previous studies demonstrating the SCD5-dependent intracellular retention of SPARC and considering the known involvement of SPARC itself in supporting a mesenchymal-like phenotype, we looked for the possible SCD5 capability in reversing the EMT-like process in melanoma." (PMID 29484133, 2018). "Interestingly, in some melanomas SNAIL and SPARC levels were not correlated, suggesting that mechanisms other than SNAIL induction may be involved in SPARC-mediated E-cadherin repression." (PMID 22911700, 2012).